PTPRH (protein tyrosine phosphatase receptor type H)
Description:
Protein phosphatase that may contribute to contact inhibition of cell growth and motility by mediating the dephosphorylation of focal adhesion-associated substrates and thus negatively regulating integrin-promoted signaling processes. Induces apoptotic cell death by at least two distinct mechanisms: inhibition of cell survival signaling mediated by PI 3-kinase, Akt, and ILK and activation of a caspase-dependent proapoptotic pathway. Inhibits the basal activity of LCK and its activation in response to TCR stimulation and TCR-induced activation of MAP kinase and surface expression of CD69. Inhibits TCR-induced tyrosine phosphorylation of LAT and ZAP70. Inhibits both basal activity of DOK1 and its CD2-induced tyrosine phosphorylation. Induces dephosphorylation of BCAR1, focal adhesion kinase and SRC. Reduces migratory activity of activity of Jurkat cells. Reduces tyrosine phosphorylation of CEACAM20 and thereby contributes to suppress the intestinal immune response CEACAM20 (By similarity).
Synonyms: R-PTP-H; SAP-1; SAP1
Tractability: Antibody: its Gene Ontology location is reachable by antibodies, with high confidence; UniProt places it where antibodies can reach, with medium confidence; UniProt predicts a signal peptide or a membrane-spanning region.
Gene: Protein-coding gene on chromosome 19 (55,181,230 to 55,209,508, reverse strand). Ensembl gene ENSG00000080031.
Subcellular location: Cell projection, microvillus membrane; Apical cell membrane; Cytoplasm
Subcellular location (Human Protein Atlas): Cytosol; Nuclear speckles; Plasma membrane
Gene Ontology:
Molecular function: cadherin binding; protein binding; protein tyrosine phosphatase activity; transmembrane receptor protein tyrosine phosphatase activity
Biological process: axon guidance; protein dephosphorylation; signal transduction
Cellular component: cytosol; plasma membrane; apical plasma membrane; cytoplasm; microvillus; microvillus membrane
Genetic constraint (gnomAD): Loss-of-function variants: 114 observed, 137.13 expected, observed/expected ratio (o/e) 0.83, 90% interval 0.71 to 0.97. The upper end of that interval is the gene's LOEUF score, 0.97, which puts it in group 4 of 6, group 1 being the genes least tolerant of losing a copy. Missense variants: 1,430 observed, 1,476.2 expected, observed/expected ratio (o/e) 0.97, 90% interval 0.93 to 1.01. Synonymous variants: 556 observed, 597.93 expected, observed/expected ratio (o/e) 0.93, 90% interval 0.87 to 1.
Homologues: Orthologues: chimpanzee PTPRH (96% identical), macaque PTPRH (76% identical), pig PTPRH (64% identical), dog PTPRH (54% identical), mouse Ptprh (51% identical), rat Ptprh (49% identical). Paralogues in human: PTPRJ (27% identical), PTPRB (26% identical), PTPRF (21% identical), PTPRO (20% identical), PTPRD (20% identical), PTPRS (19% identical), PTPRT (19% identical), PTPRM (18% identical), PTPRK (18% identical), PTPN13 (18% identical), PTPRU (17% identical), PTPRZ1 (16% identical), and 23 more.